TNF (tumor necrosis factor)
Diseases named in the same sentence as TNF in open-access papers (continued):
Sharing a sentence is not in itself a finding about the gene and the disease.
Klebsiella Infections (4 papers, 2012 to 2024). Infections with bacteria of the genus KLEBSIELLA. "Several pro-inflammatory cytokines including IL-6, IL-1β, and TNF-α were also decreased after astragaloside IV treatment, indicating that astragaloside IV could inhibit inflammation-related apoptosis caused by Klebsiella infection by inhibiting TGF-β1 signaling pathway." (PMID 37493767, 2023). "Previous studies revealed that TRIF- and MyD88-dependent TLR signaling, which stimulate proinflammatory cytokines TNF-alpha and IL-6, contribute to host defense against Klebsiella infection." (PMID 22427976, 2012). "TAU treatment also reduces the expression levels of markers such as inducible nitric oxide synthase (iNOS), nuclear factor kappa-B (NF-κB), TNF-α and IL-2 during acute inflammation and has been shown to reduce TNF-α, IL-1β and IL-6 levels in Klebsiella infections." (PMID 39614280, 2024). "While the Baran paper demonstrated that IFI207-depleted cells had lower levels of TNFα and IFNβ1 in response to LPS or K. pneumoniae, IFI207 knockout mice in their study sustained lower levels of Klebsiella infection than WT mice." (PMID 38860764, 2024).
laryngeal squamous cell carcinoma (4 papers, 2013 to 2023). A squamous cell carcinoma that arises from the larynx. "Geopropolis has also been found to be cytostatic towards human laryngeal epidermoid carcinoma cells and is known to stimulate tumor necrosis factor alpha (TNF-α) and interleukin-10 (IL-10) production by human monocytes." (PMID 29125569, 2017). "Laryngeal squamous cell carcinoma (LSCC) mice model was established by using BALB/c mice which different transfected Hep-2 cells with pcDNA3.1 (+) containing TNF-α and/or CD were applied subcutaneously." (PMID 23593411, 2013). "Studies of laryngeal squamous cell carcinomas have shown that TAN effect decreased CD4+/CD8+ T cell and inhibit production of TNF-α and IFN-γ, resulting in an immunosuppressive environment." (PMID 36765760, 2023).
Left ventricular dilatation (4 papers, 2022 to 2025). Enlargement of the chamber of the left heart ventricle. "Pro-inflammatory cytokines, such as TNF-α and IL-1β, cause cardiac myocyte hypertrophy, contractile dysfunction, and left ventricular dilatation and modulate the interstitial matrix of the heart." (PMID 38813367, 2024). "These authors demonstrated that TNF-α blockade decreased left ventricular dilation, which was associated with a decrease in the production and activity of MMP-9." (PMID 35372112, 2022). "TNF-α, a negative inotropic factor, can cause left ventricular dilation and enlarged end-diastolic diameter." (PMID 40821638, 2025).
LGL leukemia (4 papers, 2008 to 2024). "Other cytokines, such as IL-8, IL-10 and TNF-α, appear to be increased in LGL leukemia cultures as well, when compared to healthy controls and seem to inhibit hematopoiesis." (PMID 38610985, 2024). "The proposed mechanism for the development of AIHA in LGL leukemia involves the overproduction of multiple cytokines by LGLs, including IL-1, TNF-α, IFN-γ, and IL-10, which leads to the production of autoantibodies against erythrocytes." (PMID 38610985, 2024). "Another possible explanation for the co-occurrence of LGL leukemia and RA is that LGL leukemia develops as a result of the immunomodulating therapies used to treat RA, namely treatment with tumor necrosis factor (TNF) inhibitors." (PMID 35646651, 2022). "Regardless of the mechanism for their development, the lack of specificity of these clonally expanded LGL cells for RA or LGL leukemia suggests that anti-TNF inhibitor therapy is not likely to be the mechanistic link between RA and T-LGL leukemia." (PMID 35646651, 2022).
malaise (4 papers, 2011 to 2024). A feeling of general discomfort or uneasiness, an out-of-sorts feeling. "Therefore, it is plausible to speculate that chronic expression and circulation of HIV-1-related proteins causes liver inflammation (as reflected by high TNFα expression) and malaise." (PMID 21978457, 2011).
MALT lymphoma (4 papers, 2015 to 2024). An indolent, extranodal type of non-Hodgkin lymphoma composed of small B-lymphocytes (centrocyte-like cells). "In the present cluster analysis, the TNF-α signaling via NF-κB showed a significant difference in the pathway activation in orbital MALT lymphoma as compared to that observed with conjunctival MALT lymphoma." (PMID 38322414, 2024).
melanosis (4 papers, 2014 to 2025). "With respect to those networks, SLs are very similar to UVB-melanosis except for the causative cytokines such as TNFα for the increased production of EDN1 and SCF." (PMID 31357457, 2019). "Inflammatory cytokines such as Tumor Necrosis Factor-alpha (TNF-α) modulate MITF expression and activity, contributing to the pathogenesis of melasma." (PMID 39940926, 2025). "We consistently observed that AOPT‐LTL treatment significantly reduced mast cell infiltration and the release of pro‐inflammatory cytokines (TNF‐α, IL‐1β, IL‐6) and the expression of key enzymes regulating inflammatory mediators (iNOS, COX‐2) in a guinea pig model of melasma." (PMID 40916844, 2025). "In UVB-melanosis and in solar lentigo, EDN1 and membrane-bound SCF (mSCF) are up-regulated at the production and/or secretion levels due to the UVB-stimulated release of interleukin (IL)-1 and the UV-independent secretion of tumor necrosis factor α (TNFα), respectively." (PMID 24823877, 2014).
meningococcal meningitis (4 papers, 2012 to 2024). "In meningococcal meningitis patients, low TNF-α production is associated with tenfold increase in mortality whereas the severity of the disease is directly proportional to the TNF-α levels in CSF and blood of JE patients." (PMID 22276993, 2012). "Meningococcal meningitis is characterized by elevated levels of pro-inflammatory cytokines like tumor necrosis factor α (TNF-α), interleukin-1β (IL-1β), and IL-6 within cerebrospinal fluid (CSF)." (PMID 39877376, 2024). "However, the severity of meningococcal meningitis is directly correlated with the production of IL-1β, TNF-α, IL-6 and IL-8." (PMID 26316174, 2015).
Middle East respiratory syndrome (4 papers, 2020 to 2023). A viral respiratory infection that is caused by the MERS coronavirus (MERS-CoV), which most often manifests with moderate to severe respiratory symptoms, including productive cough and shortness of breath, which can progress to pneumonia and acute respiratory distress syndrome. "This includes the pro-inflammatory cytokines such as interleukin (IL)-1, IL-6 and tumor necrosis factor (TNF)-α, as well as the inflammatory chemokines CCL-2 and CXCL-10, which have previously been seen in other coronavirus infections such as Middle East respiratory syndrome (MERS)." (PMID 35054471, 2022).
nasal obstruction (4 papers, 2024 to 2025). "A logistic regression model showed that only serum TNF‐α levels and the severity of nasal obstruction significantly differentiated patients with N‐ERD from the other groups." (PMID 41179970, 2025). "Of the factors identified as differentiating patients with N‐ERD from other study participants, only the severity of nasal obstruction and serum TNF‐α levels were entered into the model." (PMID 41179970, 2025). "TNF-α was positively correlated with nasal obstruction (r = 0.4389, P = 0.0046)." (PMID 39525400, 2024).
nephrosis (4 papers, 2014 to 2024). Pathological processes of the KIDNEY without inflammatory or neoplastic components. "Moreover, TNFα levels correlated with severity of proteinuria (r2 = 0.594; p = 0.02), suggesting that elevated TNFα levels contribute to the development of proteinuria, and possibly nephrosis, in Blk+/−." (PMID 24637841, 2014).
nephrotoxicity (4 papers, 2019 to 2024). Toxicity that causes injury to the kidney or damages its function. "Pioglitazone reduced the mRNA levels of pro-inflammatory cytokines (IL-6 and TNF-α) and increased the mRNA levels of anti-inflammatory cytokines (IL-4 and IL-10) in an in vitro model of calcium oxalate monohydrate-induced nephrotoxicity." (PMID 39621679, 2024). "However, TNF-α levels significantly decreased in the groups treated with Cis + Infliximab and Cis + MSCs compared to the Cis-induced nephrotoxicity rat model (p < 0.05)." (PMID 36425134, 2022). "Groups treated with Cis + Infliximab-labeled PEG-coated SPIONs-loaded MSCs showed kidney weights and concentrations of TNF-α, Na, BUN, creatinine, and uric acid in serum were significantly declined compared to the Cis-induced nephrotoxicity rat model." (PMID 36425134, 2022).
neuroma (4 papers, 2022 to 2024). A tumor that grows from a nerve or is composed of nerve cells and nerve fibers. "TNF-α and IL-1β may contribute to neuroma-associated neuropathic pain." (PMID 37048560, 2023). "After adding the HUD antibody, the levels of factors secreted by M1 macrophages TNF-α (P < 0.01) and IL-12 (P < 0.05) in co-cultured neuroma cells and monocyte macrophages increased significantly, while the level of factor secreted by M2 macrophage IL-10 (P < 0.05) decreased." (PMID 35294333, 2022). "Furthermore, local inflammation has been heavily implicated in neuroma pain, with upregulation of pro-inflammatory cytokines such as TNF-α and downregulation of IL-10 in painful versus non-painful neuroma tissue samples." (PMID 38749904, 2024).
normal tension glaucoma (4 papers, 2009 to 2024). "In normal-tension glaucoma (NTG) patients, presence of central scotoma (p = 0.029) was significantly associated with positive TNF-α level." (PMID 36079162, 2022).
ocular toxoplasmosis (4 papers, 2010 to 2022). Ocular toxoplasmosis is an infection in the eye caused by the parasite, Toxoplasm a gondii. "The high expression level of TNF-α in patients with cerebral or ocular toxoplasmosis further confirmed the role of tachyzoites secretions in the induction of TNF-α production." (PMID 35565525, 2022). "This study was aimed to analyze the synthesis of Interferon gamma (IFN-γ), Tumor Necrosis Factor alpha (TNF-α), and Interleukin 10 (IL-10) in chronically infected patients which developed the symptomatic disease as cerebral or ocular toxoplasmosis." (PMID 25352834, 2014). "There was no more ocular toxoplasmosis compared to other clinical forms whether the patient treatments comprised corticosteroids, anti-TNF-α or antimetabolites, alone or associated." (PMID 35939518, 2022). "Moreover, mice with diminished expression of Beclin 1 and mice with inactivation of Atg7 in microglia/macrophages are susceptible to cerebral and ocular toxoplasmosis despite upregulation of IFN-γ, TNF-α and NOS2 as well as the induction of T cell-mediated immunity." (PMID 21217818, 2010). "This study analyzed the synthesis of Interferon gamma (IFN-γ), Tumor Necrosis Factor alpha (TNF-α), and Interleukin 10 (IL-10) in chronically infected patients which developed the symptomatic disease as cerebral or ocular toxoplasmosis." (PMID 25352834, 2014).
opioid use disorder (4 papers, 2018 to 2025). A substance-related disorder that involves the recurring use of opioids despite negative consequences. "The randomized, double-blind, sham-controlled clinical trial investigated the effects of bilateral tDCS on craving, tumor necrosis factor-alpha (TNF-a) and interleukin-6 (IL-6) expression levels, and impulsivity in adult males with opioid use disorder (OUD)." (PMID 40725591, 2025). "We analyzed catalase (CAT), glutathione (GSH), malondialdehyde (MDA), superoxide dismutase (SOD) activity (as oxidative markers) and also MMP-9 and TNF-α level in the plasma of patients with opioid use disorder during two weeks of methadone therapy." (PMID 29892317, 2018). "The plasma TNF-α level in patients with opioid use disorder was higher (199.96±69.14 pg/mL, p<0.05) compared to the smoker or non-smoker comparison groups." (PMID 29892317, 2018). "Nonetheless, other studies indicate that in patients with opioid use disorder, an analysis of memory ability shows a negative correlation with TNF-α and IL-6 levels." (PMID 39857699, 2025).
oral epithelial dysplasia (4 papers, 2016 to 2023). "Studies of premalignant oral lesions in patients and in a murine oral model of premalignant oral lesions have shown an increased inflammatory state that is characterized by increases in levels of inflammatory cytokines such as IL-6, TNF-α and IL-17." (PMID 27453801, 2016). "The significantly reliable and valid values suggest that salivary TNF‐α can be used as a biomarker for OSCC and oral epithelial dysplasia." (PMID 37199052, 2023). "The results showed a dependence on IL-23 signaling for the pro-inflammatory state of mice with oral lesions as levels of IL-2, IFN-γ, IL-6, IL-17 and TNF-α were elevated in wildtype mice with premalignant oral lesions, but not in IL-23R KO mice." (PMID 29664967, 2018).
panic disorder (4 papers, 2015 to 2022). An anxiety disorder characterized by multiple unexpected panic attacks with persistent concern of recurring attacks. "In particular, patients with panic disorder (PD) present an inflammatory response due to elevated levels of pro‐inflammatory cytokines, such as interferon gamma (IFN‐γ), tumor necrosis factor alpha (TNF‐α), interleukin (IL) 6, and IL‐1β." (PMID 35588458, 2022). "Activated CD8+ T cells can secrete TNF-α and IFN-γ in response to inflammation, we observed lower CD8+ T cell proportions in panic disorder cases, consistent with lower levels of IFN-γ in PD cases observed in prior work." (PMID 33208194, 2020).
Papillary Thyroid Cancer (4 papers, 2016 to 2025). "In summary, low concentration of TNF-α can induce EMT in different papillary thyroid cancer cell lines." (PMID 33854637, 2021). "The results of this part together suggested that TNF-α successfully induced epithelial mesenchymal transition in papillary thyroid carcinoma cells, and optimal results of various marker protein level could be obtained under the concentration of 20 ng/mL." (PMID 33854637, 2021). "But whether TNF-α can induced EMT in papillary thyroid carcinoma and the possible mechanisms involved are still unknown." (PMID 33854637, 2021). "In order to explore whether TNF-α plays a key role in the process of epithelial mesenchymal transition (EMT) in papillary thyroid carcinoma (PTC), we used TNF-α to induce EMT in different PTC cell lines, and observed the expression of different transcription factors and signal pathways." (PMID 33854637, 2021). "Circulating levels of TNF-α and the adhesion molecules L-Selectin and VCAM-1 as well as their expression in the primary tumors of patients with benign thyroid diseases and papillary thyroid carcinoma (PTC) have been determined in this study." (PMID 26881177, 2016).
PASH syndrome (4 papers, 2019 to 2024). "Anti-TNF agents such as infliximab and adalimumab are the most prescribed medications to treat PASH syndrome, usually with varying success." (PMID 38878169, 2024). "The PG lesion of PASH syndrome patients shows significantly elevated levels of inflammatory cytokines and mediators, including IL‐1β, TNF‐α, IL‐17, IL‐8, MMP‐2, and MMP‐9, compared to healthy skin." (PMID 38031879, 2024). "Given the wide variability of PASH syndrome’s genetic background, PG, and its syndromic form PASH may constitute a spectrum of polygenic autoinflammatory disorders, as supported by the overexpression of proinflammatory cytokines IL-1β, IL-17, and TNFα, in affected patients." (PMID 38250061, 2023).
phlebitis (4 papers, 2017 to 2023). Inflammation of a vein. "Mirabilite can significantly reduce the expression levels of interleukin (IL)-1, IL-6, and tumor necrosis factor-α (TNF-α) in mechanical phlebitis caused by a venous indwelling needle, and reduce the inflammatory response in rabbit ear vein." (PMID 37532999, 2023). "Monocytes/macrophages in FIP phlebitis were also shown to strongly express TNF-α." (PMID 33121170, 2020). "Activated and FCoV-infected monocytes can induce phlebitis through the paracrine and autocrine action of CD18, IL-1β and TNFα." (PMID 28388950, 2017).
poisoning (4 papers, 2011 to 2025). A condition or physical state produced by the ingestion, injection, inhalation of or exposure to a deleterious agent. "A single nucleotide polymorphism in TNF-α was previously associated with susceptibility to bone marrow dysplasia in chronic benzene poisoning." (PMID 21147609, 2011). "Blockers of TNF-α may be useful in patients with paraquat poisoning." (PMID 24039983, 2013).
postpartum depression (4 papers, 2023 to 2024). A type of clinical depression that occurs after childbirth. "Third, an elevation in TNF-α blood levels in women during the perinatal period had a protective effect on the emergence of postpartum depression." (PMID 38586283, 2024). "Mangiferin treatment suppresses microglial activity and downregulates the levels of TNF-α, IL-6, and IL-1β in the hippocampus of mice with postpartum depression." (PMID 38915473, 2024). "Hypericin, one of the rich compounds in CS extract, has been reported to be able to alleviate the symptoms of postpartum depression as effective as fluoxetine by decreasing the levels of inflammatory factors (IL-6, IL-1β, TNF - α) in serum." (PMID 36909192, 2023).
pregnancy disorder (4 papers, 2020 to 2025). A disorder that is related to pregnancy. "Cohort studies have reported no relevant difference between peri-conceptional paternal exposure to different anti-TNFα and undesirable pregnancy outcomes or congenital malformations with rates comparable to population rates." (PMID 34122062, 2021). "Women affected by pregnancy disorders exhibit an enhanced inflammatory state, as well as elevated levels of pro-inflammatory cytokines, such as TNF-α and IL-6, systemically and locally in the placenta." (PMID 32570911, 2020). "In addition, data from medical records concerning pregnant women exposed to immunosuppressive drugs included 56 womens with first trimester exposure to anti-TNFα who showed no significant increased risk in fetal adverse events or congenital malformations." (PMID 34122062, 2021). "Recent studies demonstrated that some adipokines such as resistin, visfatin and tumor necrosis factor α (TNF-α) are dysregulated in GDM and contribute to metabolic complications typical of this pregnancy disorder." (PMID 34652617, 2021). "A growing number of studies suggest that various adipokines including adiponectin, leptin, visfatin, resistin and tumor necrosis factor α (TNF-α) are dysregulated in GDM and might have pathological significance and a prognostic value in this pregnancy disorder." (PMID 34652617, 2021).
proctitis (4 papers, 2016 to 2025). An inflammatory process affecting the anus. "A set of biomarkers (pro-hepcidin, IL-6, TNF, hemoglobin, ferritin, transferrin) and genetic polymorphisms were linked to proctitis." (PMID 40506902, 2025). "Advancement flap use is recommended when used with immunotherapy/anti-TNF drugs, but its use is not possible when the fistula tract is fibrotic, or there is proctitis." (PMID 36284816, 2022).
progressive multifocal leukoencephalopathy (4 papers, 2011 to 2024). Progressive multifocal leukoencephalopathy (PML) is a neurological disorder that damages the myelin that covers and protects nerves in the white matter of the brain. "To date, TNFα-blocking agents administration is the most promising therapy, although these treatments are associated with an increased Polyomavirus JC (JCPyV) reactivation, the etiological agent of the Progressive Multifocal Leukoencephalopathy (PML)." (PMID 27242700, 2016).
protein (4 papers, 2021 to 2025). "In contrast, folate deficiency significantly increased pro-inflammatory cytokine IL-6 and TNF-α secretions which were not significantly affected by HFF." (PMID 37630806, 2023). "Additionally, protein–energy malnutrition may induce a high level of systemic inflammatory factors, such as tumor necrosis factor (TNF)-α and interleukin-6, can facilitate tumor cell proliferation invasion and metastasis, and can enhance malignant properties." (PMID 34765561, 2021).